SMPD5 (sphingomyelin phosphodiesterase 5 (pseudogene))
Synonyms: SMPD5P; MA-nSMase
Gene: Transcribed unitary pseudogene on chromosome 8 (144,049,079 to 144,051,203, forward strand). Ensembl gene ENSG00000204791.
Diseases named in the same sentence as SMPD5 in open-access papers:
SMPD5 is named in the same sentence as 2 diseases in open-access papers, as found by Europe PMC text mining. Sharing a sentence is not in itself a finding about the gene and the disease. The quoted sentences say what the papers report.
breast carcinoma (1 paper, 2018). "We found that SMPD2, SMPD4, and SMPD5 were significantly higher in breast cancer tissue than that in paired normal breast tissue, while SGMS2 was significantly decreased in breast cancer tissue (TCGA cohort, n=112)." (PMID 29731990, 2018).
Insulin resistance (1 paper, 2023). Increased resistance towards insulin, that is, diminished effectiveness of insulin in reducing blood glucose levels. "Mitochondrial overexpression of SMPD5 induces insulin resistance by lowering CoQ9 in L6 myotubes." (PMID 38149844, 2023).